MIF (macrophage migration inhibitory factor)
Diseases named in the same sentence as MIF in open-access papers (continued):
Sharing a sentence is not in itself a finding about the gene and the disease.
melanoma (continued). "We have also previously reported compromised outcomes in patients with constitutive expression of inducible nitric oxide synthase (iNOS), macrophage migration inhibitory factor (MIF) and better outcomes with CD74 expression in stage III melanoma." (PMID 33327409, 2020). "Intriguingly, in melanomas, the expression of CD74, the main receptor of MIF, correlated with a favorable patient outcome." (PMID 31013837, 2019). "Another, previously studied, CDR peptide (C36L1) showed ability to bind to MIF's receptor CD74 and also interfere in the melanoma-secreted factor that regulates macrophage function." (PMID 32010152, 2019). "In vitro analysis conducted in human melanoma cell lines showed that MIF acts upstream of the PI3K/AKT pathway, as MIF knock-down decreased AKT phosphorylation." (PMID 31013837, 2019). "Thus, MIF targeting therapies could provide a new effective way of treating melanoma." (PMID 31013837, 2019). "The macrophage migration inhibitory factor (MIF) is synthesized by epithelial and endothelial cells, T lymphocytes, macrophages, and by several tumors, particularly melanoma." (PMID 32010152, 2019). "In melanoma-bearing mice, administration of 4-IPP led to attenuated TAM polarization, immunosuppression, neo-angiogenesis and melanoma outgrowth, offering MIF inhibition as an interesting target for further investigation." (PMID 28471401, 2017). "Here, MIF was characteristically found within “tunnels” in MTF nuclei, both in cultured MTFs as well as in apparent MTFs in primary melanomas, and in the SK-MEL cells lines." (PMID 26267609, 2015). "We specifically selected these two mouse models in order to be able to compare our results on ISO-66 with already reported data, in which MIF shRN A and ISO-1 were used to block MIF in similar in vivo melanoma and colon cancer models, respectively." (PMID 25050663, 2014). "Here, CTCs were enriched (∼400X) from blood of melanoma patients using a simple centrifugation device (OncoQuick), and 4 melanocyte target RNAs (TYR, MLANA, MITF, and MIF) were quantified using QPCR." (PMID 22829910, 2012). "Our results indicate that ∼1/3 of melanoma patients (nearly all of them early stage) have significantly elevated levels of MLANA and MIF marker RNAs compared with healthy volunteers, and similar results have been reported in a number of other studies." (PMID 22829910, 2012). "In this study, we evaluated if the combination of anti-MIF and anti–programmed cell death 1 (anti–PD-1) therapies could synergistically reduce tumor progression in the immune-responsive YUMMER1.7 melanoma and the MC38 colorectal carcinoma murine models." (PMID 41122966, 2025). "Mice with YUMMER1.7 melanomas and MC38 colorectal carcinomas treated with anti–PD-1/anti-MIF had trends toward slower tumor growth, more complete tumor regression, and prolonged survival when compared with those treated with monotherapy (anti–PD-1 or anti-MIF alone) or isotype control." (PMID 41122966, 2025). "To better investigate the effect of anti-MIF on the TME, we subcutaneously injected YUMMER1.7 melanoma cells into mice and treated them for either 1 week (2 doses, short treatment) or 2 weeks (4 doses, long treatment) before isolating tumors for single-cell RNA-Seq (scRNA-Seq) analysis." (PMID 41122966, 2025). "Prior studies have shown that MIF expression levels are elevated in patients with melanoma, however no prior studies have reported simultaneous DDT expression levels in these patients." (PMID 39028303, 2024). "Prior research has shown that MIF levels are elevated in patients with melanoma, but DDT levels have not been similarly explored." (PMID 39028303, 2024). "Thus, CD74:MIF and CD74:DDT expression ratio measurements offer promise as prognostic markers for survival outcomes and ICI response in patients with melanoma." (PMID 39028303, 2024).
melanoma (continued). "In melanoma, MIF is present across UV- and non-UV-induced melanomas, where enrichment in serum and tumor is correlated with advanced stages, poor survival, and resistance to immune checkpoint inhibition (ICI)." (PMID 38732068, 2024). "Furthermore, MIF and DDT hold potential as biomarkers to prognosticate response to ICI and survival in patients with melanoma." (PMID 39028303, 2024). "Targeting MIF and DDT may further offer benefit to patients with melanoma subtypes that are traditionally unresponsive to standard therapy, such as uveal, mucosal, and acral subtypes, and tumors harboring different mutational signatures." (PMID 39028303, 2024). "Given the link between TIMP-1 and enhanced immunogenicity in melanoma, its interaction with CD74 might either bolster its MHC-I/II chaperoning role or compete with MIF, reducing MIF-induced suppressive effects through CD74." (PMID 38777826, 2024). "In melanoma and esophageal squamous carcinoma, blocking the MIF/CD74 signaling pathway inhibited AKT phosphorylation and promote tumor progression, whereas, in glioma, the MIF/CD74 axis inhibited IFN-γ secretion by promoting the phosphorylation of ERK1/2." (PMID 38685050, 2024). "Pharmacologic blockade of the MIF/DDT-CD74 signaling axis could potentially alter the immunosuppressive TME and offer new therapeutic options for melanoma." (PMID 39028303, 2024). "Finally, the expression levels of SNAI2, MMP2, MIF, and AP1S2 were elevated in melanoma cells of MM, consistent with the results of previous studies." (PMID 37880239, 2023). "The Fab portion of mAbs can be used to block signaling pathways which promote melanoma growth and survival, for example blocking TAM chemoattractant pathways, blocking immunoregulatory axes such as SIPRα/CD47 and inhibiting immunoregulatory MIF." (PMID 36211808, 2022). "Although neither of these mechanisms of inhibiting MIF have yet been translated to clinical trials in melanoma, a phase 1 clinical study of an anti-MIF mAb in solid tumors has recently been completed, with results awaited (NCT01765790)." (PMID 36211808, 2022). "Although a number of markers on EVs have been identified for a particular type of tumour (for example: EpCAM for ovarian cancer; VLA-4, TYRP2 and MET for melanoma; MIF for PDAC), so far, no universal markers have been found." (PMID 33081785, 2020). "Other than that, ROR1, FOXC1, MIF, TGFβ, lncRNA SNHG17, MIAT, MHENCR, OR3A4 and H19 regulate proliferation, progression, migration, invasion, metastasis or EMT-like transition though PI3K/AKT pathway in melanoma cells." (PMID 32333246, 2020). "In this current study, we have identified and validated the protein expression of CD74 (and together with MIF) as providing survival information, and propose that CD74+ and MIF− together be considered to form a “signature” for stage IV melanoma prognosis, as we found on stage III melanoma." (PMID 33327409, 2020). "Moreover, TSA significantly inhibited MIF expression also in HaCat keratinocytes, HL-60, KG1a and U-937 leukemic cell lines, THP-1 monocytic cells, A549 airway epithelial cells and B16 melanoma." (PMID 31635049, 2019). "In addition, it has been shown that in melanoma, IFN-gamma increases cell surface expression of CD74, and the interaction with its ligand MIF activates the PI3K/AKT pathway, promoting tumour survival." (PMID 29707160, 2018). "Furthermore, MIF may be involved in cell proliferation and differentiation and several studies have reported increased MIF mRNA levels in tumor cells and pre-tumor states in prostate, colon, and hepatocellular cancers, adenocarcinomas of the lung, glioblastomas and melanomas." (PMID 26883190, 2016). "We hypothesize that they form very early on at the periphery of melanomas, locally induce the EMT, and readily enter the circulation, subsequently colonizing distant sites and secreting cytokines such as MIF." (PMID 26267609, 2015).
melanoma (continued). "Comparison of MelCV and Me1007 melanoma cells transfected with MIF-25 siRNAs confirmed a substantial reduction in the total MIF protein measured in cell lysates relative to negative control (NC) siRNA treatment (respectively)." (PMID 25168062, 2014). "In contrast to these studies, in our protocols, we administered ISO-66 daily and for 20 consecutive days, to significantly, if not completely, inactivate MIF constantly produced both by the host and by melanoma or colon cancer cells." (PMID 25050663, 2014). "Further, as early-stage melanomas develop, immature melanocyte migration into the blood is somehow curtailed, whereas a significant proportion of patients develop elevated CTC levels (based on MIF and MLANA RNAs)." (PMID 22829910, 2012). "The expression of pyruvate kinase, HSP90 alpha, MIF, and STAT1 in primary and metastatic melanomas could be demonstrated by IHC staining." (PMID 19221597, 2009). "The cytokine MIF (macrophage migration inhibitory factor) and its cognate receptor CD74 are intimately connected with cancer progression and have previously been proposed as prognostic biomarkers for patient outcome in various cancers, including solid tumors such as malignant melanoma." (PMID 38730725, 2024). "Dual MIF and DDT blockade may provide synergistic responses in patients with melanoma, irrespective of common mutations, and may overcome ICI resistance." (PMID 39028303, 2024). "In addition, MIF and CD74 have been identified as potential targets of anti-cancer therapeutics, including for cervical cancer, ovarian carcinoma, glioblastoma, multiple myeloma, and melanoma." (PMID 38730725, 2024). "Furthermore, MIF and DDT may contribute to ICI resistance in melanoma and pancreatic cancer through T cell suppression and exhaustion, emphasizing the need to target these cytokines and restore antitumor immunity in the TME." (PMID 38732068, 2024). "Furthermore, obstructing MIF/CD74-induced signalling in the TME emerges as a promising method to boost melanoma immunogenicity, irrespective of a vaccination strategy (GVAX)." (PMID 37454231, 2023). "Monocyte-derived MIF is reported centrally involved in human monocytic MDSC induction/immune suppressive function and that targeting MIF may provide a novel means of inducing anti-tumor responses in late stage melanoma patients." (PMID 36845727, 2023). "Experiments have shown that knocking down MIF expression in cells inoculated in mice led to similar-sized tumors establishing horizontally, but the vertical growth was strongly decreased, compared to mice inoculated with no-knock down melanoma cells." (PMID 31013837, 2019). "MIF plays a key role in the development of metastatic disease by regulating angiogenesis and immunity, as well as by activating, through its binding to the CD74 receptor, the MAPK and the PI3K/AKT pathways, which are the most important signaling pathways in the development of melanoma." (PMID 31013837, 2019). "Uveal melanoma is not the only type of melanoma to produce MIF." (PMID 31013837, 2019). "In fact, it is known that the local production of pro-inflammatory cytokines such as MIF and TNF in the tumor microenvironment of solid tumors such as GBM and melanoma induce the production of NO and other immunosuppressive mediators that may favor growth and invasiveness of GBM." (PMID 30441775, 2018). "We could not establish that the sensitivity of individual melanoma cell lines to MIF depletion resulted from the differential expression of known MIF receptors (i.e. CD74/CD44 and/or CXCR4)." (PMID 25168062, 2014). "Kaplan-Meir plots of MIF levels against survival appeared to show no predictive significance of MIF levels in primary melanoma tumours whereas a clear trend was evident for metastatic samples where the first and second quartiles segregated from the third and fourth quartiles." (PMID 25168062, 2014).
melanoma (continued). "Here we verified these data using independent expression microarray datasets where collectively these findings support the general concept that MIF is differentially expressed between non-malignant and malignant lesions with increased expression during melanoma progression." (PMID 25168062, 2014). "While MIF transcripts may serve as a good marker for early stage melanoma, the sources of MIF are not clear; MIF is also elevated in the SCC/NF patient samples." (PMID 22829910, 2012). "However, the clinical significance of high MIF expression in melanoma has not been reported." (PMID 25168062, 2014). "Indeed, CD74 expression is associated with melanoma progression but, as previously seen (Section 2.1), high levels of CD74 in melanoma metastasis are associated with a better overall and recurrence-free survival, in the absence of MIF in the tumor microenvironment." (PMID 31013837, 2019). "This analysis also does not factor in epigenetic regulators of MIF expression or expression of the MIF homolog DDT (or MIF-2), which also engages the cognate MIF receptor CD74 and is expressed in many tumor types, including melanoma." (PMID 41122966, 2025).
pancreatic cancer (84 papers, 2009 to 2026). "Recent research reported that macrophage migration inhibitory factor (MIF) played a critical role in the differentiation of MDSCs caused by exosomes in pancreatic cancer." (PMID 39611045, 2024). "Glypican 1 (GCP1) and macrophage migration inhibitory factor (MIF) were identified as potential exosome-associated biomarkers for early diagnosis of pancreatic cancer." (PMID 36770959, 2023). "High levels of exosomal MIF in patients with stage I pancreatic cancer has been associated with liver metastasis." (PMID 36167539, 2022). "MIF is up-regulated in patients with pancreatic cancer and causes dysfunction of insulin secretion in β-cells." (PMID 24708788, 2014). "It is known that pancreatic tumor cells express high levels of damage-associated molecular patterns (DAMPs) and pro-inflammatory factors, such as macrophage migration inhibitory factor (MIF)." (PMID 35140221, 2022). "MIF over-expression is associated with reduced E-cadherin expression and increased vimentin expression, indicative of epithelial-to-mesenchymal transition characteristics thus enhanced invasiveness in pancreatic cancer cell lines." (PMID 33776775, 2021). "In another study it was found that MIF increased pancreatic cancer progression and metastasis via AKT/ERK (Extracellular signal-regulated protein kinases)/CCND1 (Cyclin D1)/MMP-2 (Matrix metalloproteinase-9) axis." (PMID 41159021, 2025). "Our single-cell ligand-receptor bubble plot analysis showed that in pancreatic cancer epithelial cells, the expression levels of MIF, MDK, and LGALS9 were significantly higher when NAT10 and KRT8 were highly expressed than when they were low-expressed." (PMID 41203621, 2025). "Notably, the MIF signaling pathway was significantly implicated, suggesting a protumor function for fibroblasts—especially cancer-associated fibroblasts (CAFs)—and macrophages, as well as a pivotal role for MIF in modulating immune responses and promoting pancreatic tumor cell proliferation." (PMID 41008826, 2025). "Pancreatic tumor exosomes carrying MIF home to the liver and specifically interact with Kupffer cells (resident hepatic macrophages), triggering the release of TGF-β." (PMID 40574836, 2025). "In pancreatic cancer, EVs containing macrophage inhibitory factor (MIF) selectively interact with Kupffer cells in the liver, leading to TGF-β secretion." (PMID 40574836, 2025). "In pancreatic cancer cell lines, MIF stabilizes the structure of HIF-1α through CSN5, which in turn further up-regulates the expression of MIF." (PMID 41210694, 2025). "Another investigations reported that, serum MIF showed higher levels in pancreatic cancer cells than normal cells and also correlated with poor survival and poor prognosis and so can be a non-invasive diagnostic and prognostic biomarker for pancreatic cancer." (PMID 41159021, 2025). "In pancreatic cancer, up-regulation of TA-MSCs enhances macrophage migration inhibitory factor (MIF) expression and promotes the malignant biological behavior of tumors by increasing levels of FTO." (PMID 39033180, 2024). "In pancreatic cancer, exosome proteins are reported to be in an elevated form as macrophage migration inhibitory factor (MIF) compared with healthy subjects." (PMID 38770216, 2024).